LINC02582 (long independently transcribed non-coding RNA 2582)
Synonyms: CTD-2354A18.1
Gene: Long non-coding RNA gene on chromosome 18 (73,324,757 to 73,392,162, forward strand). Ensembl gene ENSG00000261780.
Diseases named in the same sentence as LINC02582 in open-access papers:
LINC02582 is named in the same sentence as 2 diseases in open-access papers, as found by Europe PMC text mining. Sharing a sentence is not in itself a finding about the gene and the disease. The quoted sentences say what the papers report.
breast carcinoma (2 papers, 2019 to 2021). "LINC02582 functionally serves as a molecular target of miR-200c, which has been previously demonstrated as a radiosensitizer in breast cancer." (PMID 34575114, 2021). "Among the differentially expressed lncRNAs, we identified lncRNA LINC02582 as a downstream target of miR-200c and LINC02582 was required for radioresistance in breast cancer cell." (PMID 31601781, 2019). "In summary, the ATM/ZEB1/USP7/CHK1, miR-200c/LINC02582/USP7/CHK1, USP7/PHF8, UCHL3/RAD51, USP52/ASF1A, and UCHL1/HIF-1 signaling axis are potential targets to improve the radiosensitivity of breast cancer." (PMID 34575114, 2021). "We also identified LINC02582 as a link between miR-200c, CHK1, and radioresistance of breast cancer cells." (PMID 31601781, 2019).
LINC02582 also shares sentences with these, for which no sentence is quoted: tumor (1 paper).